MIR7703 (microRNA 7703)
Synonyms: hsa-mir-7703
Gene: MicroRNA gene on chromosome 14 (24,143,489 to 24,143,565, reverse strand). Ensembl gene ENSG00000283856.
Homologues: Orthologues: chimpanzee MIR7703 (100% identical).